DYRK1B (dual specificity tyrosine phosphorylation regulated kinase 1B)
Diseases named in the same sentence as DYRK1B in open-access papers (continued):
Sharing a sentence is not in itself a finding about the gene and the disease.
tumor (continued). "In addition, DYRK1B protein expression was elevated in tumor tissues compared to that in adjacent normal tissues of TNBC patients." (PMID 34830933, 2021). "CCDC97 and ZNF581 were positively correlated with DYRK1B expression and might be involved in DYRK1B-mediated tumor malignancy in TNBC patients, providing DYRK1B as a potential theranostic target for TNBC." (PMID 34830933, 2021). "Also, DYRK1B expression was significantly elevated in tumor tissues of any other subtypes except TNBC." (PMID 34830933, 2021). "Indeed, a differential expression analysis using TCGA data finds DYRK1B to be overexpressed in several tumor types, including bladder (BLCA); breast (BRCA); kidney (KICH, KIRC and KIRP); liver (LIHC); prostate (PRAD); thyroid (THCA) and uterus (UCEC)." (PMID 32751160, 2020). "Likewise, DYRK1B knockdown negatively affects PDAC cell proliferation, migration and invasion, whereas a treatment of PANC1 xenografts with a DYRK1B inhibitor impairs tumor growth." (PMID 32751160, 2020). "In addition, Dyrk1B inhibits cell cycle progression in G0/G1 in some tumor cells by phosphorylation of p27Kip1." (PMID 24676346, 2014). "Altogether, there is increasing evidence that inhibition of Dyrk1B, possibly in combination with Dyrk1A, might represent a promising, yet underexploited anti-tumor strategy." (PMID 24676346, 2014). "Also, Ccdc97 and Znf581 were positively correlated with Dyrk1B expression and might be involved in Dyrk1B-mediated tumor malignancy in patients with TNBC, suggesting Dyrk1B as a potential therapeutic target for TNBC." (PMID 38675189, 2024). "In this article, we outline the well-established cell-autonomous roles of DYRK1B and extend its importance to the TME and the control of the tumor immune stroma." (PMID 39863750, 2025). "This difference is reminiscent of the DYRK kinase family, in which DYRK1A usually acts as an oncogene, while DYRK1B and DYRK3 inhibit tumor progression." (PMID 35092699, 2022). "Thus, DYRK1B may confers to tumor progression of TNBC and result in worse survival." (PMID 34830933, 2021). "Both DYRK1A and DYRK2 showed a significantly lower expression in READ tumor vs. normal tissues, whereas DYRK1B, DYRK3 and DYRK4 had no significant change in expression." (PMID 35454940, 2022). "The DMR is situated within the DYRK1B gene, approximately 200 kbp distal to the DLL3 TSS, and is significantly correlated with DLL3, but not DYRK1B, gene expression in both primary tumor samples and cell lines." (PMID 32707835, 2020). "However, the unbiased analysis of differentially expressed genes in human tumour samples has revealed that the expression of DYRK1B, but not DYRK1A, is elevated in various types of solid tumours." (PMID 39397076, 2024). "However, DYRK1B levels are also increased in many tumours without corresponding copy number changes of 19q138." (PMID 39397076, 2024). "Likewise, formation and growth of U87MG multi‐cellular tumour spheroids in lower (2% compared to 10%) FCS resulted in a similar decrease in Rb S807/811 phosphorylation, total Rb and cyclin D1 protein and an increase in DYRK1B and p27 expression." (PMID 34708541, 2021). "In contrast, DYRK1B and DYRK4 tumor expression was not correlated to MYCN amplification status, and DYRK1A was actually lower in tumors with MYCN amplification." (PMID 29977157, 2018).
neurodegenerative disease (2 papers, 2017 to 2024). A disorder of the central nervous system characterized by gradual and progressive loss of neural tissue and neurologic function. "Although loss-of-function mutations are typically inherited in a recessive fashion, it is possible that mutant DYRK1B aggregation constitutes a gain of toxic function, similar to mutant tau or synuclein in familial forms of neurodegenerative diseases." (PMID 28743892, 2017).
cardiovascular disease (1 paper, 2025). "However, there remains a paucity of data on myocardial DYRK1B expression in patients with cardiovascular disease in the context of other comorbidities." (PMID 40002350, 2025).
infection (1 paper, 2024). The state of being infected such as from the introduction of a foreign agent such as serum, vaccine, antigenic substance or organism. "In a previous study, we showed that the AD169 and Merlin infection of TEV-1 cells resulted in cellular re-localization and accumulation of DYRK1A and DYRK1B." (PMID 38932210, 2024).
liver (1 paper, 2022). "Taken together, these results indicate that Dyrk1b causes liver IR by inducing plasma membrane sn-1,2-DAG/PKCε–dependent impairment of IRK activity, while its suppression protects against diet-induced hepatic IR." (PMID 34855620, 2022).
metabolic disorders (1 paper, 2025). "Research has also identified genetic variations and mutations in the DYRK1B gene associated with metabolic disorders." (PMID 40799825, 2025). "Targeting DYRK1B and its associated pathways may hold promise for the development of novel therapeutic strategies for treating metabolic diseases and improving metabolic health." (PMID 40799825, 2025). "However, further investigation using expanded omics approaches will be necessary to elucidate the broader roles and functions of DYRK1B in various cellular-stress pathways relevant to metabolic disorders, as well as its potential as a diagnostic or prognostic biomarker." (PMID 40799825, 2025). "Dual-specificity tyrosine phosphorylation-regulated kinase 1B (DYRK1B) is implicated in metabolic diseases, with high expression linked to adipocyte differentiation and metabolic disorders." (PMID 40799825, 2025). "In this context, advances in heteroaryl medicinal chemistry have facilitated the development of selective kinase inhibitors capable of precisely targeting emerging regulators such as DYRK1B, underscoring its therapeutic potential in addressing the multifactorial nature of metabolic disorders." (PMID 40799825, 2025).
DYRK1B also shares sentences with these, for which no sentence is quoted: Abdominal obesity (6 papers); coronary artery disease (4); hypertriglyceridemia (2); atrial fibrillation (1); autosomal dominant mental retardation (1); basal cell carcinoma (1); Childhood onset (1); dilated cardiomyopathy (1); Ewing sarcoma (1); glioblastoma (1); head and neck squamous cell carcinoma (1); heart diseases (1); lipoma (1); lymphoma (1); meningioma (1); motor neuron diseases (1); non-small cell lung carcinoma (1); nonalcoholic fatty liver disease (1); ovarian tumors (1); prostate carcinoma (1); triple-negative breast carcinoma (1).